COL3A1 (collagen type III alpha 1 chain)
Diseases named in the same sentence as COL3A1 in open-access papers (continued):
Sharing a sentence is not in itself a finding about the gene and the disease.
liver fibrosis (54 papers, 2012 to 2025). "COL3A1 induction can meet the requirements for induced drastic enlargement of liver fibrosis in rats because COL3A1 encodes collagen 1(III) chain, a precursor of collagen III, and serves as a ‘cell-binding’ of tissues." (PMID 35628233, 2022). "Intriguingly, we found that LAPNTG mice are protected from liver fibrosis as reflected by a greatly reduced expression of fibrotic genes such as Col1a1, Col3a1, Col4a4, TGF-β, and SMA." (PMID 39792554, 2025). "Liver fibrosis in NAFLD is caused by liver inflammation, and major markers of fibrosis are Col1a1, Col3a1, and Tgfβ1." (PMID 37894124, 2023). "In the GSE55747 database, we found that EBI3, COL1A1 and COL3A1 mRNA expressions in mice of the liver fibrosis group were also higher than those of the normal group." (PMID 37480105, 2023). "The temporal CDAHFD-feeding experiment revealed that Dbn1 expression was induced as the hepatic fibrosis progressed, along with increase in Col1a1 and Col3a1 expression." (PMID 36690273, 2023). "The qRT-PCR assays showed that Dbn1, Col1a1, and Col3a1 expression levels increased during CCl4-induced hepatic fibrosis." (PMID 36690273, 2023). "COL3A1 encodes collagen α-1(III) chain, a precursor of collagen III, which serves as a ‘cell-binding’ of tissues, the induction of COL3A1 expression plays a crucial role in the drastic enlargement of liver fibrosis in rats." (PMID 34944582, 2021). "CAPN2, as a subtype of CAPN, played a crucial role in the expression of hepatic fibrosis markers, including COL3A1, COL1A1 and MAPK1." (PMID 33836021, 2021). "Similar to the CCl4-induced fibrosis model, Med23 silencing also resulted in increasing mRNAs related to liver fibrosis, including Col1a1, Col3a1, Tgfβ1, Pdgfβ, Tgfβr1, Pdgfrβ, and Timp1." (PMID 31805036, 2019). "In line with the hepatic fibrogenesis in HFrD-fed A/AHep mice, there was strongly increased expression of liver fibrosis marker genes (Col1A1, Col3A1, Timp1 and Pdgfr-β) in the livers of the HFrD-fed A/AHep mice." (PMID 28781602, 2017). "Knockdown of HRC reduced the expression of α-SMA, along with other genes relative to liver fibrosis, such as Col1A1, Col3A1 and CTGF." (PMID 27881436, 2017). "Despite the increase in fibrosis in LysM-Wls mice, mRNA levels of the key interstitial collagens contributing to liver fibrosis, Col1a1, Col1a2 and Col3a1, were comparable between LysM-Wls and littermate controls." (PMID 26473015, 2015). "Various members of the hepatic fibrosis pathway were also differentially expressed (A2M and Col3A1 upregulated in females, and IL1R2 and EGF in males)." (PMID 23531366, 2013). "In the canonical pathway for hepatic fibrosis/hepatic stellate cell activation, COL3A1, FGFR1, and IGFBP5 (P<0.01) were involved, which indicates similarity to the biological pathways already described in ULs." (PMID 23483937, 2013). "Previous studies have shown that COL3A1 is involved in the progression of liver fibrosis." (PMID 37090703, 2023). "The results of Masson staining showed the reduction of collagen deposition in Zbp1 siRNA-GeRP-treated injured livers, which was in accordance with the decreases of Acta2 (α-SMA, the marker of liver fibrosis), Col1a1 (Col I) and Col3a1 expressions in Zbp1 siRNA-GeRPs-injection groups." (PMID 36859525, 2023). "Many predicted targets such as TIMP1, MMP2, COL1A1, MMP7, and COL3A1 have been involved in liver fibrogenesis and could be potential therapeutic targets for liver fibrosis." (PMID 35791909, 2022). "CHCHD2 knockout greatly suppressed TAA-induced liver fibrosis, as evidenced by Sirius red staining and reduced expression levels of Des, Timp1, transforming growth factor-β (Tgfb), Col1a1 (P = 0.055), and Col3a1 (P = 0.054)." (PMID 36477358, 2022).
liver fibrosis (continued). "The mRNA levels of liver fibrosis markers (Acta2, Col1a1, Col3a1, and Timp1), cholangiocyte proliferation markers (Krt7 and Krt19), inflammation markers (Il6 and Il1b), and the progenitor cell marker (Sox9) were markedly decreased in miR-200c-BDL mice compared to con-BDL mice." (PMID 34880414, 2022). "Furthermore, hepatic mRNA levels of fibrogenic genes (Acta2, Col1a1, Col3a1, Col4a1, Tgfb1, Mmp13 and Vim) were significantly upregulated in miR-223KO mice compared with WT mice, suggesting that miR-223 deletion accelerated liver fibrosis." (PMID 33867837, 2021). "Upregulation of TGFB1, TGFB2, COL1A1, and COL3A1 were found at W14 post-infection but in both infected and uninfected groups, suggesting that there may be alternative mechanisms for hepatic fibrosis in liver fluke-infected cattle." (PMID 31555289, 2019). "The qPCR results showed that overexpression of miR-552-3p significantly reduced the mRNA levels of fibrotic genes (Col1a1, Col3a1, Timp-2) and inflammatory genes (Il-6, Ccl2, F4/80) in mice livers, which demonstrated that miR-552-3p could reduce liver fibrosis and inflammation in mice again." (PMID 37496991, 2023). "Accordingly, we found increased mRNA levels of liver fibrosis (Col1a1, Col3a1, α-Sma, Tgf-β1) and HCC markers (Afp and Gpc3) at 3 months and 6 months, suggesting the successfully constructed DEN/CCl4-induced liver fibrosis and primary HCC model." (PMID 40180937, 2025). "Western blot analysis supported these findings, demonstrating that LTH-sEVshCtr further enhanced the expression of liver fibrosis markers COL1A1, COL3A1, and α-SMA protein in the liver tissue of HFD mice." (PMID 38822260, 2024). "Then, by IHC analysis, we analyzed COL1A1 and COL3A1 levels, two key components of the extracellular matrix (ECM) altered during the progression of liver fibrosis." (PMID 38539791, 2024). "The validation cohort showed GPC3 was negatively correlated with all liver fibrosis markers ACTA2, COL1A1, COL1A2, COL3A1 and ductular reaction markers KRT7 and KRT19, while SDC4 was positively correlated with ductular reaction index KRT19." (PMID 36816373, 2023). "Firstly, liver fibrosis (marker as ACTA2, COL1A1, COL1A2, COL3A1), reflected by proliferation of myofibroblasts and collagen deposition, is associated with decreased native liver survival mostly." (PMID 36816373, 2023). "Transcriptional levels of liver fibrosis markers (ACTA2, COL1A1, COL1A2, COL3A1) and ductular reaction markers (EPCAM, KRT7, KRT19) were significantly upregulated in BA." (PMID 36816373, 2023). "Animal experiments have shown that quercetin can ameliorate liver fibrosis by inhibiting HSCs activation and ECM formation and regulating COL1A1, COL3A1, MMP9, and TIMP1 mRNA expression levels." (PMID 35791909, 2022). "We also found slight increase in COL3A1 and CXCR4 both of which play important roles in hepatic fibrosis." (PMID 30024933, 2018). "Similarly, the expressions of the genesCOL1A1,COL3A1,ACTA2,DES,TGFβ1, andVIM, which are involved in liver fibrosis, increased in liver organoids treated with 100 mM and 200 mM ethanol." (PMID 38818583, 2024). "Similarly, S. japonicum miR-29b-3p prevents parasite-induced liver fibrosis by inhibiting COL1A1 and COL3A1." (PMID 37490505, 2023). "Furthermore, it was observed that the levels of Acta2, Col1a1, Col3a1, Tnfa, Il6, and Il1β genes were significantly increased upon STAT3 overexpression, again suggesting that STAT3 mitigated liver fibrosis." (PMID 36588728, 2022). "Additionally, roseotoxin B also reduced the expression level of liver fibrosis-related α-SMA, Col1A1 and Col3A1 in the PDGF-BB-activated CFSC-8B cells." (PMID 32541811, 2020). "In mice, DPP4is decrease liver fibrosis; however, this was not recapitulated by genetically eliminating Dpp4 as Picrosirius red staining revealed a trend toward increased fibrosis, and expression of Col1a1 and Col3a1 was increased in Dpp4–/– mice." (PMID 36472923, 2023).
liver fibrosis (continued). "In addition, the transcript levels of liver fibrosis-related genes such as collagen type I alpha 1 chain (Col1a1) and collagen type III alpha 1 chain (Col3a1) were significantly downregulated by YC-1102, indicating that YC-1102 could inhibit NASH-induced liver fibrosis." (PMID 38921022, 2024). "Doing so, we found that the deletion of adiponectin in HSCs accelerates the development of liver fibrosis as reflected by significant increases in SMA, Col1a1, Col3a1, Col4a4, and leptin, but not TGF-β expression in the liver." (PMID 39792554, 2025).
breast carcinoma (34 papers, 2014 to 2025). "COL3A1 is highly expressed by the tumour stroma and associated with increased survival in breast cancer patients." (PMID 36190948, 2022). "Collagen factors COL1A1, COL1A2, and COL3A1 were often implicated in carcinogenesis or metastasis in a variety of tumor types, for instance breast cancer, gastric cancer, and cervical cancer." (PMID 36059672, 2022). "Secreted COL3A1 causes a wavy collagen fiber orientation promoting tumour dormancy in breast cancer possibly through a DDR pathway (Discoidin domain receptor—tyrosine kinase proteins activated by collagen) to limit metastasis." (PMID 36190948, 2022). "In contrast, the expression of COL3A1 was previously indicated in breast cancer where was associated with tumor development and progression and with the resistance to CIS in ovarian cancer." (PMID 30583585, 2018). "Type III collagens (COL3A1) are associated with more benign, non-invasive breast cancers, and expression of type I collagens (COL1A1) are associated with invasive phenotypes." (PMID 29854878, 2018). "Using gene co-expression analysis, we showed that P4HA2 was associated with expression of Col1A1, Col3A1, and Col4A1 during breast cancer development and progression." (PMID 24383403, 2014). "COL3A1 has been significantly associated with breast cancer brain metastases in multiple studies." (PMID 36553667, 2022). "COL3A1 has also been reported in other cancer types such as breast and colorectal cancers, with an association between COL3A1 and P4HA2 with poor prognosis in breast cancer, and correlation between elevated epithelial COL3A1 protein expression and unfavorable outcome in colorectal cancer." (PMID 31533654, 2019). "Regarding COL3A1, Wu and Zheng found that COL3A1 is one of the key genes relating to the brain metastasis process in breast cancer." (PMID 38187400, 2023). "COL3A1 was overexpressed in lymph nodes affected by metastatic ductal breast carcinoma cells, and also in DCIS myoepithelial cells compared with normal mammary myoepithelium." (PMID 36278695, 2022). "Another study has shown that when Pirfenidone, an anti-fibrotic drug, was applied to breast cancer to investigate its possible role on tumor microenvironment normalization, the level of COL3A1 was down-regulated, thereby inhibiting the TGFβ signaling pathway." (PMID 32766145, 2020). "COL3A1 can also be considered to be a potential biomarker for colon cancer, breast cancer and brain tumor." (PMID 32429941, 2020). "In breast cancer, it was reported that stromal COL3A1 expression was significantly increased from benign breast tumors to malignant breast tumors." (PMID 32766145, 2020). "For example, an L-FFL motif comprised of the lncRNA H19, the TF MYC and the miRNA miR-29c, and an ceRNA motif comprised of the mRNA COL3A1, the lncRNA H19 and the miRNA miR-29c, were both dysregulated in breast cancer." (PMID 27322142, 2016). "Similarly, COL3A1 has been reported to have an important role in breast cancer progression as knockdown studies in triple-negative breast cancer cell lines have been linked to reduced invasion and proliferation." (PMID 38928454, 2024). "COL3A1, COL11A1, and FBN1 are associated with maintaining a cancer stem-like phenotype in various cancers and therefore may be of interest in breast cancer." (PMID 35755802, 2022). "Both COL3A1 and ROR2 have been implicated in breast cancer pathogenesis." (PMID 36190948, 2022). "In breast cancer, it was found that methyltransferase-like 3 could target COL3A1 in triple-negative breast cancer cell lines." (PMID 35047627, 2021). "A report indicated that COL3A1 gene has prognostic implications in breast cancer." (PMID 34229299, 2021). "In addition, COL3A1, COL4A1, COL5A1, and COL15A1 are associated with immune infiltration in head and neck squamous cell carcinoma, breast cancer, mesothelioma, and other tumors." (PMID 34691289, 2021).
breast carcinoma (continued). "Finally, the relationship between METTL3 and COL3A1 in breast cancer was analyzed with Pearson correlation analysis." (PMID 32766145, 2020). "Here, we showed that expression of P4HA2 and collagen genes (Col1A1, Col3A1, and Col4A1) is significantly correlated during breast cancer development and progression, and that increased mRNA levels of P4HA2 are associated with poor prognosis in breast cancer patients." (PMID 24383403, 2014). "Through an integrated analysis of transcriptomics data, we identified a special subgroup of EMP1+/COL3A1+ fibroblasts that are enriched in breast cancer BoM samples, which might facilitate the BoM process through interacting with tumor cells via COL3A1-ADGRG1 communication." (PMID 38187400, 2023). "COL3A1 expression could have implications as a vital biomarker in breast cancer." (PMID 36190948, 2022). "COL3A1, also known as type III collagen, is abundant in blood vessels and plays a key role in breast cancer metastasis." (PMID 40433364, 2025). "According to the xiantao database, COL1A2, COL3A1, FGA, LUM, APOA1, APOH, and COL5A2 were more highly expressed in breast cancer than in normal tissues (p < 0.05), while the opposite pattern was seen for ALB and FBN1 (p < 0.05)." (PMID 37079213, 2023). "Among different subgroups in breast cancer scRNAseq data, significant correlations between EMP1/COL3A1 and three EMT genes (CDH1, VIM, and CTNNB1) were found in c16 fibroblasts." (PMID 38187400, 2023). "While collagen type I is well described as having a role in cancer cell proliferation, drug resistance, and motility, the matrix proteins such as COL3A1, COL11A1, FBN1, and MFAP2 are less explored in breast cancer." (PMID 35755802, 2022). "For relapse-free survival, breast cancer patients with higher expression of VEGFA, EZH2, CASP3, WWP1, CUL2, and COL3A1 had poorer prognosis." (PMID 35812757, 2022). "In order to verify the effects of METTL3 and COL3A1 on the prognosis of breast cancer patients in vivo, the expression of METTL3 and COL3A1 was investigated by immunohistochemistry using TMA sections containing 31 TNBC patients and 109 Non-TNBC patients." (PMID 32766145, 2020). "Next, we analyzed the correlation of compression-upregulated metabolic genes with compressive stress markers (COL1A1, COL3A1, HAS2, and HAS3 genes) and tumor size in breast cancer subtypes: luminal A (LumA), luminal B (LumB), Her2, and triple-negative (TN)." (PMID 31428701, 2019). "Collagen type III alpha-1 chain (COL3A1) functions in cell adhesion, migration, proliferation and differentiation by its interations with collagen-binding integrins, which are transmembrane receptors mediating cell adhesion and breast cancer development." (PMID 36278695, 2022). "When we further interrogated the expression of collagen genes commonly expressed in breast cancer ECM (COL1A1, COL1A2, COL3A1 and COL5A1) we observed decreased endogenous gene expression of these collagens in higher passage TU-BcX-4IC tumors compared to lower passage." (PMID 34370182, 2022). "Physical interaction networks however detected only COL3A1, suggesting it could be a gene of interest that CTHRC1, POSTN and MMP13 could use to regulate the tumour matrisome in breast cancers." (PMID 36190948, 2022). "Among the compression-upregulated metabolic genes, the expression of ENO2 gene was significantly and positively correlated with COL3A1 and HAS1 genes, whereas PFKFB3 genes were significantly and positively correlated with that of COL1A1, HAS2, and HAS3 genes in breast cancer patient tissues." (PMID 31428701, 2019). "Since the COL3A1 and COL1A2 genes are both in the pathway of scavenging by class A receptors, which are important regulators of immune responses to cancer, their co-expression changes in the tumor tissue may help us better understand the immune response processes in breast cancer." (PMID 34252628, 2021).
breast carcinoma (continued). "Finally, with immunohistochemistry staining in breast cancer tissues, it was proved that METTL3 expression was negatively correlated with COL3A1 in TNBC, but not in non-TNBC." (PMID 32766145, 2020).